IL6 (interleukin 6)
Diseases named in the same sentence as IL6 in open-access papers (continued):
Sharing a sentence is not in itself a finding about the gene and the disease.
metabolic syndrome (continued). "Meanwhile, dyslipidemia associated with decreased ADIPOQ expression in EAT and PVAT, LEPR in EAT, and IL6 in PVAT." (PMID 36157437, 2022). "The study showed that the five classified types of dyslipidemia had increased circulating levels of IL-6, TNF-α, and MCP-1 compared with a normal lipid group in male adults." (PMID 36032093, 2022). "Conversely, dyslipidemia was associated with a 2.1-fold (p = 0.014) decrease in LEPR mRNA in EAT and 2.3-fold decrease in IL6 in PVAT (p = 0.023)." (PMID 36157437, 2022). "Current research provides links among dyslipidemia and elevated levels of low-grade chronic inflammatory cytokines, such as interleukin IL-6, TNF-α, and CRP." (PMID 34299655, 2021). "The concentrations of IL-6 and TNF-α are associated with dyslipidemia, a factor that compromises endothelial function." (PMID 34526542, 2021). "Adiponectin, leptin, resistin, TNF-α and IL-6 are considered as possible serum markers of metabolic syndrome and their expression levels are majorly regulated by SREP-1c and PPAR-γ." (PMID 33917607, 2021). "The supplementation with L. reuteri V3401 (5 × 109 CFU for three months) in patients with metabolic syndrome resulted in IL-6 and soluble vascular cell adhesion molecule 1 (sVCAM-1) decrease associated with a rise in the proportion of Verrucomicrobia." (PMID 33717063, 2021). "In our previous research, we documented the associations of plasma concentrations of interleukin 6 (IL-6) and tumour necrosis factor α (TNF-α), together with its soluble receptors, with components of metabolic syndrome in patients with CAD." (PMID 34679472, 2021). "It is known that serum IL-6 levels are elevated in metabolic syndrome, cardiovascular diseases and chronic inflammatory airways diseases." (PMID 33763027, 2021). "Adults with metabolic syndrome were administered L. reuteri in a separate study, wherein microbiome composition was altered in addition to decreases in IL-6 and soluble vascular adhesion molecule 1 as metabolic syndrome symptom markers." (PMID 33815818, 2021). "This study therefore expands upon our previous work and aims to examine the effects of combined supplementation with FG and ω-3 PUFA on dyslipidemia, transaminases, interleukin-6, and oxidative stress in pre-obese rats." (PMID 33557198, 2021). "A study on females with metabolic syndrome found that a 12 week-long aerobic exercise intervention promotes a decrease in IL-6." (PMID 34948558, 2021). "Aboonabi and Aboonabi found a similar result—they recorded a significant downregulation of TNF-α, IL-6 and IL-1A gene expression after supplementing 320 mg anthocyanins for 4 weeks in subjects with metabolic syndrome." (PMID 34444991, 2021). "In fact, inflammatory cytokines like IL-6 were shown to link with dyslipidemia by promoting de novo hepatic fatty acid synthesis and suppressing the activity of lipoprotein lipase, a key enzyme involving in catabolism of triglyceride-rich lipoproteins." (PMID 34208976, 2021). "The NF-κB signaling pathway mediated by TNF-α can regulate lipid metabolism, and IL-6 can promote systemic inflammation, leading to metabolic syndrome and abnormal lipid metabolism." (PMID 35047504, 2021). "Liver enzymes, C-reactive protein (CRP), interleukin-6, soluble intercellular adhesion molecule-1 (sICAM-1), adipokines, and parameters related to metabolic syndrome (MetS) were all measured." (PMID 33665176, 2021). "In our study, patients with higher HO-1 plasma levels showed higher BMI values, a higher frequency of metabolic syndrome, higher levels of IL-6, and lower adiponectin." (PMID 34943105, 2021). "Inflammatory cytokines such as TNF-α, IL-6, and IL-1β play significant roles in the etiology of metabolic syndrome." (PMID 34938803, 2021). "OLE treatment to old rats not only decreased the circulating levels of IL-6 but also improved dyslipidemia reducing the plasma levels of LDL-cholesterol." (PMID 33854149, 2021).
metabolic syndrome (continued). "This study aimed to examine the effects of combined supplementation with FG and ω-3 PUFA on dyslipidemia, transaminases, interleukin-6, and oxidative stress." (PMID 33557198, 2021). "Quercetin, genistein, and naringenin alleviated TNF-α and IL-6 levels in rats with high-fructose and high-fat diet-induced metabolic syndrome rats, respectively." (PMID 34987591, 2021). "High levels of IL-6 and TNF-α in patients with metabolic syndrome are associated with truncal fat mass." (PMID 34326779, 2021). "IL-6 was elevated in a subgroup of patients with heart failure, dyslipidemia, atrial fibrillation diabetes mellitus, anemia, and chronic renal failure as already described." (PMID 33535417, 2021). "In one study on men with features of the metabolic syndrome, there was a significant inverse correlation between serum interleukin-6 (IL-6) and testosterone levels." (PMID 34360982, 2021). "Lamers and colleagues presented evidence that patients with specific atypical features show associations with immuno-metabolic outcomes including IL-6, CRP and metabolic syndrome components, both cross-sectionally and longitudinally." (PMID 33653423, 2021). "A large number of adipocytokines (leptin, adiponectin, visfatin, PAI-1, resistin, TNF-α, and IL-6) are involved in the pathogenesis of metabolic syndrome (MS)." (PMID 33584134, 2021). "Whole-body cryotherapy, assuming the application of 20 treatments in the series, reduces abdominal obesity in menopausal women indirectly through the secretion of irisin and IL-6, and can be used as adjunctive therapy in the treatment of metabolic syndrome." (PMID 32872598, 2020). "The adipokines leptin, adiponectin, tumor necrosis factor-alpha (TNF-α), and interleukin 6 (IL-6) might be associated with metabolic syndrome (MetS) in patients with schizophrenia." (PMID 33066473, 2020). "Metabolic syndrome was more prevalent (p = 0.040) and IL6 levels were higher in the hs-CRP ≥3 group (p < 0.001)." (PMID 32514365, 2020). "Intra-abdominal fat also secretes adipocytokines, such as leptin, adiponectin, resistin, and interleukins (IL-1 and IL-6), which act as energy regulators and inflammatory markers and are thus correlated strongly with metabolic syndrome." (PMID 32309767, 2020). "BMI and metabolic syndrome have been also associated with oxidative stress (MDA, MPO, CAT) and pro-inflammatory markers (IL-6, high sensitivity C-reactive protein)." (PMID 32824349, 2020). "IL-6 is a potent inducer of hepatic CRP and has been implicated in cardiovascular atherosclerotic risk, dyslipidemia and hypertension." (PMID 31293514, 2019). "One meta-analysis reported that C18:3 administration had great therapeutic potential via decreasing patients’ inflammatory markers (e.g., C-reactive protein, IL-6, and TNF-α) that were associated with metabolic syndrome and related diseases." (PMID 31182969, 2019). "The prognosis for the independent risk factors of age, IL-6, ANP, DBP and dyslipidemia were incorporated into the nomogram." (PMID 31191115, 2019). "The results revealed that high CP infection rate, dyslipidemia and the overexpression of inflammatory factors, such as IL-6, hs-CRP and tumor necrosis factor-ɑ (TNF-α), can be commonly found in patients with CHD." (PMID 31088358, 2019). "Metaflammation in adipose tissue, characterized by infiltration of macrophages, local gene expression and secretion of pro-inflammatory factors, especially IL-6 and IL-1β, is considered a potential factor contributing to development of the metabolic syndrome." (PMID 30697360, 2019). "A randomised human study of patients with metabolic syndrome demonstrated a reduction in plasma concentrations of both IL-6 and TNF-α following 45 days of oral treatment with fermented milk containing Bifidobacterium lactis." (PMID 31618905, 2019).
metabolic syndrome (continued). "In fact, a recent study conducted in morbidly obese men with metabolic syndrome showed a significant increase in the serum levels of IL-6 and IL-12, both cytokines with proinflammatory actions, without reporting any difference in IL-13." (PMID 29675435, 2018). "Dyslipidemia is promoted by sustained inflammation as certain cytokines, namely TNFa and IL6, have been shown to influence lipid levels, shifting them towards an atherogenic profile." (PMID 29954107, 2018). "The decreases in either IL-6 or TNF-α suggest reductions in subclinical inflammation, which is associated with a lower risk of metabolic syndrome." (PMID 30060746, 2018). "IL-6 is the source of the metabolic syndrome induced by inflammation, and plays a core regulatory role in the inflammatory response." (PMID 30360498, 2018). "After controlling for potential confounders, blood CRP, interleukin-6, and leptin were significant predictors of all five individual components of the metabolic syndrome (as both continuous and categorical outcome measures)." (PMID 30190688, 2018). "In a randomized, controlled dietary intervention for patients with the metabolic syndrome, bilberry supplementation reduced serum high-sensitivity C-reactive protein (CRP), IL-6, IL-12 and LPS levels, and downregulated genes associated with the TLR pathway." (PMID 30307962, 2018). "The prolonged surge in pro-inflammatory cytokines such as tumor necrosis factor-alpha (TNF-α), interleukin (IL)-1, IL-6, and interferon-alpha (IFN-α) has been linked with dyslipidemia in studies following the chronic state of the HBV-infection." (PMID 29506525, 2018). "Higher level of IL-6 related to several features of metabolic syndrome including waist circumference (r = .257; p = 0.01), BMI (r = .272; p = 0.01), fasting triglycerides (r = .155; p = 0.05) and fasting HDL cholesterol (r = -.199; p = 0.01)." (PMID 29894501, 2018). "Hepcidin levels were shown to be increased in persons with features of metabolic syndrome, but also in persons with DM type 2 with high ferritin and interleukin 6 (IL6) levels." (PMID 28841871, 2017). "This study highlights the potential therapeutic benefit of anti-IL-6 therapy in preventing atherogenesis induced by dyslipidemia and/or inflammation." (PMID 29312959, 2017). "In conclusion, this study highlights the potential therapeutic benefit of anti-IL-6 therapy in preventing atherogenesis in the mice with dyslipidemia and/or inflammation." (PMID 29312959, 2017). "Consistent with the lipolytic effect of IL-6, inhibition of IL-6R using tocilizumab in RA patients leads frequently to weight gain and dyslipidemia by increasing the levels of cholesterol and triglycerides and therefore potentially increasing CVR." (PMID 29137196, 2017). "Herein, we correlated serum tartrate-resistant phosphatase isoform 5a levels with metabolic syndrome status and made comparisons with traditional markers of inflammation, including c-reactive protein and interleukin-6." (PMID 29100456, 2017). "Adipose tissue dysfunction in subjects with nascent metabolic syndromes leads to higher secretion of adipokines, such as IL-1, IL-6, IL-8, leptin, MCP-1, PAI-1, C-reactive protein, and serum amyloid A, by subcutaneous adipose tissue." (PMID 28182687, 2017). "Visceral adipose tissue is a component of the metabolic syndrome and is a major producer of IL-6, TNF-α, and MCP-1." (PMID 28642810, 2017). "Specifically, psoriasis and metabolic syndrome display similar inflammatory profiles with Th1 and Th17 T-cells as well as overexpression of cytokines such as IL-6 and TNF-alpha." (PMID 28719618, 2017). "Pro-inflammatory cytokines can increase IL-6 production, reduce adiponectin secretion, and influence insulin sensitivity, and these factors all create conditions suited to the development of metabolic syndrome." (PMID 28840832, 2017).
metabolic syndrome (continued). "Many cytokines (e.g. interferon-γ, TNF-α, IL-6, IL-8, IL-12, IL-17, IL-19 and IL-23) involved in the pathogenesis of psoriasis are also known to contribute to the cascade of metabolic syndrome such as hypertension, dyslipidemia and insulin resistance." (PMID 27531132, 2016). "In light of the recent evidence of serum IL-6 playing a role in difficult asthma and metabolic syndrome, a small trial by Franca-Pintaet al.51 offers further insight and strategies to intervene." (PMID 27610226, 2016). "Increased IL-6 plasma levels were correlated with metabolic syndrome, but the involvement of IL-6 in the molecular mechanisms underlying the metabolic syndrome effects is not fully understood." (PMID 26035386, 2015). "Abdominal obesity is a key feature of metabolic syndrome as visceral fat is responsible for the secretion of various adipocytokines such as leptin, interleukin-6 and adiponectin." (PMID 26593941, 2015). "In fact, inhibition of COX results in decreased production of the pro-inflammatory cytokines, TNF-α, IL-6 and IL-1ß in LPS-stimulated macrophages and aspirin administration reduces plasma IL-1ß and IL-6 in patients with metabolic syndrome." (PMID 25638171, 2015). "Our results showed that apoE-/- mice receiving vehicle alone developed severe atherosclerotic lesions and dyslipidemia, with significantly up-regulated levels of IL-6, TNF-α, VCAM-1 and MCP-1." (PMID 24621517, 2014). "Second, exercise decreases blood levels of IL-6 in the metabolic syndrome and obese patients, while normal weight individuals experience increased levels of IL-6 when it is released as a myokine." (PMID 24563869, 2014). "Similar results were obtained in the research that up-regulation of pro-inflammatory cytokines like TNF-a, IL-6 and IL-12 were found in patients with dyslipidemia and in animal investigation of apoE−/− mice." (PMID 23472151, 2013). "In turn, both IL-6 and IL-1β act on the liver to produce a characteristic dyslipidemia in metabolic syndrome, one which manifests as increased very low density lipoprotein (VLDL) and decreased high density lipoprotein (HDL)." (PMID 22369568, 2011). "In analysis of our cohort characteristics, while BMI decreased with age, waist-hip ratio, and IL-6 increased with age, suggesting that central obesity (a component of the metabolic syndrome) increased with age." (PMID 21170382, 2010). "After 12–13 weeks on cafeteria diet, C57BL/6 mice had a phenotype of higher body weight, serum glucose and insulin, dyslipidemia, and had higher serum TNFα and similar IL-6 compared to normal diet controls." (PMID 18474108, 2008). "Levels of IL-6 are significantly higher in patients with dyslipidemia IIa and IIb biochemically confirmed, and IL-6 levels are significantly correlated to intima-media complex thickness." (PMID 17374166, 2007). "The metabolic syndrome is a pro-inflammatory state as evidenced by increased levels of IL-6, TNF-α, and C-reactive protein (CRP), serum amyloid A, and leptin and lower level of adiponectin." (PMID 17140429, 2006). "Gender, BMI, and the presence of metabolic syndrome affect leptin concentrations, and IL-6 may be influenced by immunosuppressive treatments like hydroxychloroquine." (PMID 40283183, 2025). "A high-cholesterol diet and dyslipidemia also adversely affect the liver, and we also observed noticeable liver damage, enhanced neutrophil infiltration, fatty liver changes, and higher inflammation (IL-6 production) in response to HCD consumption." (PMID 40699753, 2025). "In adults with metabolic syndrome, daily supplementation with 15 g of jaboticaba peel powder for 5 weeks resulted in a significant reduction in postprandial glucose area under the curve, and it decreased circulating IL-6 levels." (PMID 41375968, 2025).
metabolic syndrome (continued). "Similar levels of plasma TNF and even lower levels of IL-6, when compared to DA rats, were previously noted in naïve female AO rats, which was in contrast to data obtained in obese/metabolic syndrome models in which higher IL-6 and TNF were detected in the blood of obese animals." (PMID 40427746, 2025). "The mechanisms underlying the correlation between dyslipidemia and low testosterone levels may involve proinflammatory substances (e.g., TNF-α, IL-8, IL-6, and IL1β)." (PMID 40489567, 2025). "However, this study did not evaluate other major pathological factors associated with lifestyle-related diseases and metabolic syndrome, such as leptin, TNF-α, or interleukin-6." (PMID 40050880, 2025). "Conversely, the upregulation of proteins such as HGF and CCL19, along with increased inflammatory cytokines like IL-6, CXCL10, and CCL8, suggests an inflammatory environment that could predispose OBO individuals to the development of a metabolic syndrome." (PMID 40076884, 2025). "Therefore, in the presence of dyslipidemia, males and females had higher IL-6 and lower adiponectin serum concentrations, whereas higher CRP was observed only in males." (PMID 39936780, 2025). "Similarly, a significant increase in the mRNA expression levels of NF‐κB, IκBα, TNF‐α, IL‐1β, and IL‐6 was observed in the hypothalamus of metabolic syndrome mice." (PMID 40708775, 2025). "Indeed, elevated LPS plasma levels as well as tumour necrosis factor alpha and interleukin 6 levels have been measured in sows with such metabolic syndrome and their piglets." (PMID 39943148, 2025). "Likewise, sesamol attenuated dyslipidemia, IL-6 levels, hepatic transaminases, and alkaline phosphatase, and it normalized the arterial pressure in a dose-dependent manner." (PMID 41367395, 2025). "Many researchers consider interleukin-6 (IL-6) a marker of metabolic syndrome rather than a direct causal factor; however, during exercise, muscle fibers release IL-6 independently of tumor necrosis factor-α (TNF-α)." (PMID 41515940, 2025). "However, comparable levels of plasma TNF and IL-6 contradicted the expectation of low-grade inflammation in AO rats, at least judged by cytokine content, which is one of the hallmarks of metabolic syndrome." (PMID 40427746, 2025). "Both IL‐6 and hsCRP are commonly used as biomarkers of metabolic syndrome." (PMID 40630018, 2025). "Similarly, JUNB’s connection to the IL-6 and IL-7 pathways highlights the direct link between overexpression of IL-6 and metabolic syndrome development, suggesting JUNB’s role in metabolic status regulation through IL-6 signaling modulation." (PMID 40918148, 2025). "The findings at the 8-week revealed that the microbiota from the cohort with knee OA and metabolic syndrome correlated with elevated levels of systemic inflammatory biomarkers, such as IL-1β and IL-6, alongside heightened intestinal permeability and exacerbated OA symptoms." (PMID 39656496, 2024). "Furthermore, this is likely due to significantly elevated IL-6 values within this group of patients; it is widely recognised that cytokines can contribute to dyslipidemia." (PMID 39712508, 2024). "This suggests that IL-6 and dyslipidemia play roles in disease progression." (PMID 39429270, 2024). "In addition, several studies have related the levels of circulating IL-6 to the systemic inflammation profile of psoriasis patients, including the occurrence of psoriatic arthritis and dyslipidemia." (PMID 37634972, 2024). "lactis HN019 intake in patients with metabolic syndrome led to reduced IL-6 and TNF-α levels." (PMID 37371961, 2023). "Furthermore, increased plasma levels of pro-inflammatory cytokines, such as TNF-α and IL-6, have been reported in people with severe IR, metabolic syndrome, T2D, and age-induced IR in elderly subjects." (PMID 37110230, 2023). "Additionally, the differences in IL-6 pro-inflammatory expression were analysed in patients depending on the occurrence of metabolic syndrome." (PMID 37847180, 2023).